RNU1-84P (RNA, U1 small nuclear 84, pseudogene)
Gene: Small nuclear RNA gene on chromosome 11 (66,393,449 to 66,393,612, forward strand). Ensembl gene ENSG00000202317.
Homologues: Orthologues: macaque U1 (91% identical), guinea pig U1 (83% identical), mouse Gm25589 (74% identical), rabbit U1 (70% identical), rat U1 (68% identical). Paralogues in human: RNU1-89P (87% identical), RNU1-1 (85% identical), RNU1-2 (85% identical), RNU1-27P (85% identical), RNU1-28P (85% identical), RNU1-3 (85% identical), RNU1-4 (85% identical), RNVU1-18 (85% identical), RNVU1-29 (85% identical), U1 (85% identical), RNVU1-28 (84% identical), RNVU1-7 (84% identical), and 133 more.